CDK2 (cyclin dependent kinase 2)
Diseases named in the same sentence as CDK2 in open-access papers (continued):
Sharing a sentence is not in itself a finding about the gene and the disease.
prostate carcinoma (continued). "The results demonstrated that CDK5 still promotes tumor growth under CDK2 inhibition in a prostate cancer cell line in a 22Rv1-derived xenograft model." (PMID 31395805, 2019). "Steiner demonstrated that the overexpression of IL-6 in prostate cancer resulted in a significant increase in cell proliferation through the upregulated expression of CDK2 and increased expression of pERK." (PMID 31252615, 2019). "In summary, these results showed that deregulation of the cell cycle by inhibition of the activity of the upstream signaling molecules Cdk1 and Cdk2 is at least partly involved in NED modulation in AR-positive prostate cancer cell lines LNCaP and LAPC-4." (PMID 24884804, 2014). "However, our results suggest CDK2 is also worthy of further study and drug development efforts in prostate cancer to overcome the ENR program we identified." (PMID 40624104, 2025). "It has also been found that menthol arrests the cell cycle at the G0/G1 phase in androgen-independent prostate cancer cells and the G2/M phase in PC3 prostate cancer cells by downregulating CDK2, 4, and six and downregulating downstream signaling of polo-like kinase 1 (PLK1), respectively." (PMID 40458805, 2025). "Furthermore, high MYBL2 activity identifies prostate cancer that would be responsive to CDK2 inhibition." (PMID 39113611, 2024). "Indeed, we demonstrate that CDK2 inhibition presents a more robust antitumor response in vivo using our phenotypic prostate cancer tumor models." (PMID 39113611, 2024). "For example, CDK2 was identified as a therapeutic target in prostate cancer." (PMID 36743211, 2023). "TTK may inhibit the proliferation of prostate cancer and the progression of prostate cancer by inhibiting the expression of CDK2 and CCNE1 complex." (PMID 37682152, 2023). "Moreover, CDK2 mediates androgen-dependent inhibition of AR+, castration-resistant prostate cancer cell proliferation." (PMID 36743211, 2023). "Despite the negative regulatory effects of CDKN3 on CDK1 and CDK2, an oncogenic role for aberrant overexpression of CDKN3 has been implicated in numerous types of human cancer, including prostate cancer, gastric cancer, nasopharyngeal carcinoma, and esophageal cancer." (PMID 33468140, 2021). "Interestingly, CDK5-dependent p21CIP1 degradation resulted in subsequent CDK2 activation in the nucleus, which promotes prostate cancer growth." (PMID 31395805, 2019). "Silibinin has been reported to inhibit cell growth and induce G1 arrest in cell cycle progression of human prostate carcinoma, which was associated with decreased levels of cyclin D1, CDK4, and CDK6 and induction of Cip1/p21 and Kip1/p27, followed by increased binding with CDK2." (PMID 28030611, 2016). "This study could benefit patients with castration resistant prostate cancer by targeting Skp2, Cdk2, and cyclin A using androgen treatment." (PMID 25271736, 2014). "However, based on our observations, it is important to consider the possible effects of Cdk1 and Cdk2 inhibition in NED promotion in prostate cancer cells." (PMID 24884804, 2014). "Further studies of the mechanisms by which Cdk1 and Cdk2 are involved in the plasticity of prostate cancer cells are necessary based on the fact that different approaches to the modulation of their expression and activity were not uniformly reflected in terms of NED promotion." (PMID 24884804, 2014). "Since experiments for elucidating the involvement of Cdk1 and Cdk2 in promoting NED were performed only in AR-positive prostate cancer cell lines, investigating the AR-negative cell lines might shed more light in proposed role of Cdk1 and Cdk2 deregulation in promoting NED." (PMID 24884804, 2014). "Thus, inhibition of cyclin D1 and E and cdk2, cdk4 and cdk6 suggests that PM might inhibit proliferation by arresting prostate cancer cells in G1-phase." (PMID 25175770, 2014).
prostate carcinoma (continued). "However, a recent publication points to the accumulation of CDK1 and CDK2 in RAD001-resistant prostate cancer cells, which supports our hypothesis that the reduction of α5 evoked by long-term RAD001 exposure may cause an increase in tumour growth." (PMID 22782340, 2012). "Other possible mechanisms underlying prostate cancer resistance to CDK4/6 inhibition that may underpin these results will be explored in detail below and include upregulation of other growth factor pathways such as MAPK and PI3K, CDK2 overexpression, and loss of tumor suppressors such as Rb." (PMID 40075623, 2025). "To identify appropriate models to test the functional importance of CDK2, we first examined expression of the 308 gene ENR program in a collection of prostate cancer cell lines." (PMID 40624104, 2025). "In this study, we found that MA inhibits the expression of CDK2, CDK4, and CDK6 and enhances that of p27, Rb and p-Rb to block G1/S transition in the cell cycle of prostate cancer cells." (PMID 39624845, 2024). "Mechanistic studies showed that Co-Sp reduced the expression of cyclin D1, cyclin E, CDK4, CDK2, MMP-9, MMP-1, and Bcl-2, and increased the expression of p21, cleaved caspase-9, cleaved caspase-3, cleaved PARP, and Bax in prostate cancer cells." (PMID 37313467, 2023). "Simvastatin and lovastatin suppressed expression of CDK1, CDK2, CDK3, CDK4, and CDK6 in prostate cancer cells with reduced cell viability due to induced apoptosis and cell cycle arrest." (PMID 36946734, 2023). "In solid tumors, miR-181a has been described to play an important role in cancer progression, i.e., augmented miR-181a expression promotes prostate cancer cell proliferation by down-regulating DAX-1 expression and up-regulating PSA, CDK1, and CDK2." (PMID 32932883, 2020). "To identify the possibility of targeting prostate cancer with OTUB1/Cyclin E1 axis, we treated PC3 cell with RO-3306, a Cyclin E1/CDK2 related inhibitor, in the range dose of 0, 340 nM, 1 uM, 2 uM, 3 uM, and 5 uM." (PMID 33537306, 2020). "In prostate cancer PC-3 cells, silencing ANO1 reduced the expression of cyclin D1 (CCND1), cyclin A2 (CCNA2), CDK1 and CDK2." (PMID 27732935, 2016). "In vitro cell culture results revealed that BITC decreased DNA synthesis, as well as CDK2 and CDK4 activity in TRAMP-C2 mouse prostate cancer cells." (PMID 26907265, 2016). "This study suggests that naringenin (NAR) and oleuropein (OLE) may exert antiproliferative and regulatory effects in prostate cancer cells, and that this may be regulated by modulating miR-155-5p-mediated KRAS/CDK2 targets." (PMID 41595499, 2026). "In addition, decreased expression of Su(H) can significantly inhibit cell growth via suppression of its target genes CDK2, CDK4, CyclinD1, and Bcl-2, and upregulation of P21 and P27 to induce cell cycle arrest in prostate cancer cells." (PMID 40151788, 2025). "CDK2 suppression reduced the ENR program and viability of ENR program-high prostate cancer models." (PMID 40624104, 2025). "Moreover, it inhibited the invasion of prostate cancer cells and lowered the expression of MCM2/MCM3, PCNA, and CDK2." (PMID 37682177, 2023). "We found that some of these genes are involved in cell cycle regulation especially CDK2 protein, suggesting that CHMP4C may affect prostate cancer progression in part by regulating the cell cycle." (PMID 37388224, 2023). "Trichostatin A (TSA), a classical histone deacetylase inhibitor, and genistein, a nontoxic dietary isoflavone isolated from Genista tinctoria, inhibited the expression of MCM2 and MCM2-7 loading factors, such as cyclin-dependent kinase 2 (CDK2), in prostate cancer." (PMID 35880481, 2022). "We also noted that Ki67+ proliferating cells and the expression of cell proliferation-related proteins (CDK2, CDK4, and Cyclin A) were increased in the tumor tissues of HFD-fed mice injected with TRAMP-C2 prostate cancer cells and in the DP of HFD-fed TRAMP mice." (PMID 25912035, 2015).
prostate carcinoma (continued). "In comparison with quiescent status of prostate cancer cells, we noticed an accumulation in cyclin D1, CDK4, cyclin E and CDK2 together with the expected reappearance of phosphorylated pRb when the quiescent cancer cells were induced to re-enter the cell cycle." (PMID 26416244, 2015). "In LNCaP prostate cancer cells, reduced expression of SAM68 altered the expression of an important subset of genes involved in proliferation and apoptosis, including Bcl2L1, Clusterin, cdk2, cdk3, p16INK4, cyclin D1, Par-4, EGF and IGF-1." (PMID 25944080, 2015). "VPA diminished cdk1 in all prostate cancer cell lines, whereas cdk2 and cdk4 were reduced in DU-145 and LNCaP, but not in PC-3 cells." (PMID 21867506, 2011). "We had previously observed that NU6102 inhibited CDK1-dependent nucleolin phosphorylation and CDK2-dependent pRb phosphorylation with equal efficiency in MCF7 cells, and other studies show that 8 μM NU6102 inhibited CDK1-dependent phosphorylation in prostate cancer cells." (PMID 20010939, 2010). "The results indicated that YTHDF1 does not bind to the mRNAs of CDK2 and CDK4 in prostate cancer cells." (PMID 40251202, 2025). "We also highlight alternative cell cycle targets, such as CDK2 and CDK7, as well as novel combination trials that remain under investigation, in which CDK4/6 is used to modulate the biology of the prostate cancer cell rather than effect a cytostatic change." (PMID 40075623, 2025).
hepatocellular carcinoma (71 papers, 2011 to 2026). A malignant tumor that arises from hepatocytes. "In contrast, positive regulation of USP37 is associated with increased cyclin A/CDK2 activity and development of hepatocellular carcinoma (HCC) by the hepatitis B virus HBx oncoprotein." (PMID 34758854, 2021). "HOXA7 promotes hepatocellular carcinoma through cyclin E1/CDK2, inducing proliferation, migration, colony formation, and tumorigenesis in vivo." (PMID 39596630, 2024). "CDK2 is expressed in hepatocellular carcinoma stem cells and can promote the cycle progression of liver cancer cells." (PMID 35463358, 2022). "In our previously research, U12, a UDCA derivative, was found to show anti-hepatoma activities via mTOR/S6K1, cyclinD1/CDK2/4 and caspase-dependent apoptotic signaling pathways in hepatocellular carcinoma cells." (PMID 35056164, 2022). "In our study, EB inhibited cell proliferation by blocking the cell cycle of hepatic carcinoma cells at the S phase, and its specific mechanism involved downregulation of the expressions of CDK2 and cyclin E1." (PMID 35866605, 2022). "Recently, we identified CCNE1 and CDK2 as key factors for the initiation of hepatocellular carcinoma (HCC)." (PMID 34830835, 2021). "For example, miR-124-3p reduced the progress of hepatocellular carcinoma by inhibiting the expression of target genes, such as CDK2 and CDK4." (PMID 34582363, 2021). "The silencing of EGFR by miR-302b or siEGFR led to downregulation of proliferation-related proteins, such as AKT2, CCND1, and CDK2, and resulted in the inhibition of proliferation in hepatocellular carcinoma SMMC-7721 cells." (PMID 33688369, 2021). "Our data suggest that overexpression of CCNE1 is a key driver of hepatocarcinogenesis by promoting several oncogenic events besides hepatoma cell proliferation in a CDK2-independent manner." (PMID 34830835, 2021). "The initiation of hepatocellular carcinoma depends on E-type cyclins E1 (CcnE1) and cyclin-dependent kinase 2 (Cdk2)." (PMID 32570707, 2020). "Inhibition of UHRF1 expression reduced cell growth in hepatoma cell lines via cyclin E/CDK2/p21 axis." (PMID 32528965, 2020). "By regulating its upstream circ_0078710/miR-31, CDK2 stimulated the malignant phenotypes of hepatocellular carcinoma cells." (PMID 32699532, 2020). "Activation of ERK enhanced the expression of c-Myc that downregulated p21 and enhanced the cell cycle members cyclin-dependent kinase-2 (CDK-2) and cyclin D1 in hepatocellular carcinoma." (PMID 32443845, 2020). "Fluspirilene treatment exhibited anti-tumor activity for hepatocellular carcinoma by inhibiting CDK2 and induction of autophagy." (PMID 29340087, 2017). "In summary, the present work show that daphnegiravone D markedly suppress the proliferation and survival of hepatoma cells, and induce G0/G1 arrest by reducing the expression of cyclin E1, CDK2 and CDK4 in a p38-dependent manner." (PMID 28720813, 2017). "Ultimately, the microsatellite instability (MSI) is increased, and the interaction between RFC and PCNA or between CDK2 and CyclinE is increased in the liver cancer cells, which led to the rapid growth of hepatocellular carcinoma cells." (PMID 27782152, 2016). "Further studies show that the upregulated UCA1 promotes cell growth by facilitating G1/S transition through CDK2 in both hepatic and hepatoma cells." (PMID 27009634, 2016).
hepatocellular carcinoma (continued). "To understand if fluspirilene inhibited CDK2 activities in hepatocellular carcinoma cells, we analyzed the effect of fluspirilene treatment with concentrations of 3, 10, 30 μM for 6, 12, 24 hours on cell cycle profile in HepG2 and Huh7 cells by flow cytometry." (PMID 26147897, 2015). "It has also been reported that targeted disruption of NLK inhibits tumor cell growth by simultaneous suppression of cyclin D1 and CDK2 in human hepatocellular carcinoma, which implies the anti-tumor activity of miR-101." (PMID 25337143, 2014). "Results showed that its anti-malignancy activities were activated by mTOR/S6K1, cyclinD1/CDK2/4 and caspase-dependent apoptotic signaling pathways in hepatocellular carcinoma cells (HCC)." (PMID 25486097, 2014). "Various studies showed that WIN55212-2 has pro-apoptotic effects and results in growth arrest and downregulation of cell cycle dependent kinases like cdk2, cdk4 and cdk6 in different tumor cell lines such as HepG2 hepatoma cells." (PMID 22204398, 2011). "Other reports indicated that knocking down CCT8 significantly reduced CDK2 levels in hepatocellular carcinoma (HCC), suggesting substrate specificity variations among CCT subunits, the reasons for which remain unclear and warrant further investigation." (PMID 39928781, 2025). "In addition, tryptanthrin derivatives can reduce the expression of cycline A1, cycline B1, and CDK2, resulting in S-phase arrest in hepatocellular carcinoma cells." (PMID 38195460, 2024). "This key finding highlights a critical and unique role of CCNE1 for survival and expansion of malignant hepatoma cells in a CDK2-independent manner in vivo, which until now were only hypothesised from in vitro observations." (PMID 34830835, 2021). "Since the identification of hNatB more than a decade ago, many studies have shown that it N-terminally acetylates important proteins such as actin, tropomyosin, CDK2, and α-Syn, and its function has connections to diseases such as hepatocellular carcinoma and Parkinson's disease." (PMID 32885784, 2020). "Although the gene encoding the other subunit of CDK2, CCNE1, has been linked to poor prognosis in hepatocellular carcinoma (HCC), there is little known about the role of CCNE2 in tumor progression." (PMID 33869043, 2021). "Cyclin-dependent kinases 2/4/6 (CDK2/4/6) play critical roles in cell cycle progression, and their deregulations are hallmarks of hepatocellular carcinoma (HCC)." (PMID 33579185, 2021). "Furthermore, a cellular kinase(s) is well known to be packaged into HBV capsids (the so-called endogenous kinase), and recent evidence indicates that the cyclin-dependent kinase 2 (CDK2) represents the major endogenous kinase, at least for capsids isolated from cultured human hepatoma cells." (PMID 32226051, 2020). "We adopted the in silico approach of structure-based virtual screening and ensemble docking to repurpose approved drugs for the treatment of cancers that involve CDK2 regulation, with a major focus on human hepatocellular carcinoma (HCC)." (PMID 26147897, 2015). "In renal carcinoma and glioma, ETS1 promotes cell proliferation by up-regulating TGFα expression; in hepatocellular carcinoma, ETS1 promotes cell proliferation by activating the expressions of cyclin E and cyclin-dependent kinase 2 (CDK2)." (PMID 34889689, 2021). "The protein levels of cyclin E, cyclin D, CDK2, and CDK4 were dramatically induced upon knockdown of LINC01488 in hepatoma cells." (PMID 32575745, 2020). "Xylocydine is a novel cyclin-dependent kinase (cdk) inhibitor that induces apoptosis in hepatocellular carcinoma (HCC) cells by inhibiting Cdk1, Cdk2, Cdk7, and Cdk9 activities." (PMID 23344045, 2013). "CDK2 and CDK4 are involved in the toxic action of paclitaxel on human hepatoma cells." (PMID 41002596, 2025). "CDK2 expression showed a significant negative correlation with the area under curve (AUC) of lenvatinib response in hepatocellular carcinoma cell lines." (PMID 39716890, 2025).
hepatocellular carcinoma (continued). "ROCK2 is overexpressed in human hepatocellular carcinoma (HCC) cells, and its inhibition induces ubiquitin-mediated degradation of Cdc25A, which is responsible for cell cycle progression through the S phase via CDK2/Cyclin-E activation." (PMID 33546351, 2021). "CDK2, CDK4, CCNB1 and CCND1 can accelerate the cell cycle moving from G1 to S phase and then promote the proliferation of various cell types including mouse embryonic fibroblasts, mouse neural progenitor cells and human hepatocellular carcinoma." (PMID 34438874, 2021). "Hesperidin administration also decreased the upregulation of the expression of Akt, PI3K, and cyclin-dependent kinase-2 (CDK-2) proteins brought on by DEN and successfully retained the liver tissues’ integrity against the onset of HCC (hepatocellular carcinoma)." (PMID 37446814, 2023). "In terms of cancer transformative potential, analysis in rat embryonic fibroblasts has also suggested that this property of cyclin E may, in certain circumstances, be independent of CDK2, an observation that is also consistent with analyses conducted in hepatocellular carcinoma (HCC)." (PMID 30185601, 2018).